CALR (calreticulin)
Diseases named in the same sentence as CALR in open-access papers (continued):
Sharing a sentence is not in itself a finding about the gene and the disease.
lung carcinoma (30 papers, 2009 to 2026). "NF-ĸB transcriptional activity was found to be stimulated with CALR overexpression and reduced in CALR-deficient lung cancer cells, thereby clearly indicating CALR-dependent NF-ĸB activation." (PMID 35264066, 2022). "Modulation of IĸBa expression in association with CALR expression further validated the NF-ĸB role in lung cancer." (PMID 35264066, 2022). "In our current work, we investigated the effect of CALR expression level on lung cancer cell proliferation and its underlying mechanism." (PMID 35264066, 2022). "Moreover, within the ICD clinical setting, this positive correlation between CALR and phagocytosis-associated genes was higher for radiotherapy-treated lung cancer patients than for paclitaxel-treated ovarian cancer patients." (PMID 26314964, 2015). "Au/HA NPs and RT induced immunogenic cell death (ICD) in lung cancer cells, characterized by elevated reactive oxygen species, increased calreticulin surface expression, and extracellular adenosine triphosphate release." (PMID 41551982, 2026). "Specifically, elevated CALR expression has been demonstrated to enhance lung cancer cell proliferation by activating the NF-κB signaling." (PMID 39479348, 2024). "In contrast, oxaliplatin induced cell surface calreticulin expression in colorectal cancer and murine lung carcinoma cell lines, while docetaxel induced calreticulin cell surface expression in breast, prostate and colorectal cancer cell lines in vitro." (PMID 35986757, 2023). "Overall, our present results indicate that CALR activates NF-ĸB signaling in lung cancer cells and increase cancer cell proliferation." (PMID 35264066, 2022). "Research findings substantiated a relevant correlation between lung cancer progression and clinical outcome with CALR abnormal expression." (PMID 35264066, 2022). "To evaluate the effect of CALR in lung cancer, we first examined the CALR expression in pan-cancer including LUAD and LUSC cohort." (PMID 35264066, 2022). "To further understand the mechanical role of CALR in lung cancer, we adopted the TCGA-LUAD and TCGA-LUSC cohort to sort the dysregulated signaling cascades during lung malignancy by GSEA analysis." (PMID 35264066, 2022). "CALR can not only serve as a potential prognostic biomarker for lung cancer but is also an important target for tumour immunotherapy." (PMID 36291587, 2022). "Conclusively, our results the role of CALR in lung cancer cells, indicating that highly expressed CALR proliferation at least by activation of NF-ĸB signaling pathway." (PMID 35264066, 2022). "To further dissect the effect of CALR expression on functions of lung cancer cells, we overexpressed CALR in A549 cells and knocked out CLAR in A549 and H1299 cells." (PMID 35264066, 2022). "After a series of bioinformatics analysis of CALR in lung cancer, we further explored CALR-mediated activation of the NF-ĸB signaling pathway in lung cancer progression." (PMID 35264066, 2022). "Mechanically, the NF-ĸB signaling pathway was found to be involved in CALR-regulated lung cancer progression." (PMID 35264066, 2022). "Investigations revealed the involvement of CALR in diverse types of malignancy, including lung cancer." (PMID 35264066, 2022). "At present, the function of the CALR gene on lung cancer cell invasion and metastasis is yet to be studied." (PMID 35264066, 2022). "Our in vivo assays further demonstrated that CALR depletion impaired the tumorgenesis of lung cancer." (PMID 35264066, 2022). "In lung cancer, CALR mediates TGF-β1-induced EMT by modulating the Smad and calcium signaling pathways." (PMID 33221760, 2020). "In our study, we observed that low-dose gemcitabine treatment enhanced the immunogenicity of lung cancer by increasing the exposure of calreticulin, high mobility group box 1, and upregulating expression of NKG2D ligands." (PMID 32161598, 2020).
lung carcinoma (continued). "CALR expression has been reported to be both significantly higher in breast, pancreatic and lung cancers and significantly lower in prostate tumor tissue when compared to normal prostate." (PMID 29443896, 2018). "Along similar lines, healthy individuals have been shown to differ from lung carcinoma patients with respect to the circulating levels of soluble CALR, as well as to the amount of CALR expressed on the surface of pulmonary (normal versus malignant) cells." (PMID 26300886, 2015). "The over-expression of CALR occurs in several malignancies, such as breast, prostate, liver, bladder, and lung cancers." (PMID 24884814, 2014). "Overall, CALR has a potential promoting role in the advancement of lung carcinoma." (PMID 35264066, 2022). "Previous evidence recognized the involvement of CALR in lung cancer." (PMID 35264066, 2022). "Similarly, oxaliplatin upregulated cell surface calreticulin expression in colorectal cancer and murine lung carcinoma cell lines, while docetaxel increased calreticulin cell surface expression in breast, prostate and colorectal cancer cell lines." (PMID 35366537, 2022). "This induction of the UPR and correlations of FVIII with P4HB, HSPA5 and CALR levels may also take place systemically in patients with lung cancer." (PMID 34066760, 2021). "CALR has been reported as a potential biomarker in lung cancer." (PMID 34660305, 2021). "In another study, it was shown that calreticulin overexpressed in lung cancer A549 cells significantly activated TGF-β1-induced EMT in a calcium-dependent manner; this mechanism was realized via calreticulin-mediated modulation of both Smad signaling and Ca2+ influx and Ca2+ signaling." (PMID 32268506, 2020). "In this context, our finding of reduced calreticulin expression in lung cancer cells could be of particular importance." (PMID 19236728, 2009). "In addition, the CALR deferential expression in lung cancer was valuable in lung cancer diagnosis." (PMID 35264066, 2022). "Our findings, thus, corroborated the hypothesis that CALR modulated NF-ĸB events in lung cancer." (PMID 35264066, 2022). "Moreover, CALR has been investigated in lung cancer and pancreatic cancer." (PMID 36338983, 2022). "Ginsenoside Rg3 can induce ICD in lung carcinoma cells via the mediated induction of apoptosis and a subsequent increase in the expression of the chaperone protein calreticulin (CRT) and heat shock proteins (HSPs) on the surface of lung carcinoma cells." (PMID 38361933, 2024). "Other research revealed that CALR regulated EMT through modulating Smad signaling and calcium signaling in lung cancer cells and via TGF-β/Smad3/NRP1 pathway in nasopharyngeal carcinoma cells." (PMID 35641480, 2022). "Elevated levels of ER chaperones P4HB, CALR and HSPA5 indicated the induction of the ER unfolded protein response (UPR) in platelets of patients with lung cancer." (PMID 34066760, 2021). "In the current study, FVIII was also significantly increased in the plasma of patients with lung cancer and showed a predominant correlation with the ER proteins HSPA5 and CALR in comparison to all other proteomic investigated platelet proteins." (PMID 34066760, 2021). "Accordingly, lower levels of ITGA2B and increased levels of the ER proteins P4HB, CALR and HSPA5 in patients with lung cancer and LA suggest some common affected pathways in their prothrombotic pathology." (PMID 34066760, 2021). "For pathophysiological explorations of platelet proteome changes in patients with lung cancer we concentrated on four candidates described to be involved in the processing of coagulation proteins, which are F13A1 and the ER proteins P4HB, CALR and HSPA5." (PMID 34066760, 2021).
lung carcinoma (continued). "On the basis of above results, we set out to determine whether CALR expression could predict the tendency of a subset of patients with non-small cell lung cancer (hereafter refer to as lung cancer) or ovarian cancer to respond to ICD-inducers but not non-ICD inducers." (PMID 26314964, 2015). "Like most chemotherapeutic drugs, the first-line chemotherapeutic drug for lung cancer, cisplatin (CDDP), is not able to induce ICD because it cannot induce the exposure of calreticulin (CRT) on the cell surface." (PMID 36057637, 2022).
thrombosis (29 papers, 2014 to 2026). "Half of our six patients who developed thrombosis during follow-up (all in the ET group) had mutations in the CalR gene (two with CalR Type 1 mutation and one with CalR Type 2)." (PMID 40572650, 2025). "CALR mutation (HR: 6.0, p < 0.001) and a history of thrombosis (HR: 3.8, p = 0.015) were associated with sMF risk." (PMID 40074852, 2025). "Together, our findings not only confirm differential thrombosis risk according to driver mutation, but also identify TN patients to have a lower risk of thrombosis, akin to those with CALR mutation." (PMID 38238303, 2024). "Our observations corroborate the salutary effects of aspirin with respect to both arterial and venous thrombosis, and also suggest possible benefits from aspirin prophylaxis in “very low risk” CALR-mutated patients." (PMID 38238303, 2024). "Of note, the incidence of both arterial and venous thrombosis was lower in CALR mutated and TN patients, compared to JAK2 and MPL mutated." (PMID 38238287, 2024). "Additional analyses revealed that the apparent differences in arterial and venous thrombosis observed among type 1/type 1-like CALR-mutated and TN cases, were fully accounted for by aspirin use (p value adjusted for aspirin use = 0.40/0.31)." (PMID 38238303, 2024). "On the other hand, comparison of CALR-mutated and TN patients revealed the former to be associated with male gender, higher hemoglobin level, and lower rates of arterial and venous thrombosis and major hemorrhage history." (PMID 38238303, 2024). "At the time of diagnosis, approximately 22% of patients displayed history of major arterial (14%) or venous (10%) thrombosis, 8% major hemorrhage, and 29%, microvascular symptoms; incidences of major thrombosis and hemorrhage were lower in CALR-mutated cases." (PMID 38238303, 2024). "Patients carrying CALR mutations are known to be at lower risk of thrombosis than patients with JAK2V617F." (PMID 36908768, 2023). "•Patients with MPN with CALR mutations are at lower risk of thrombosis than patients with JAK2V617F." (PMID 36908768, 2023). "In ET, patients with CALR mutations showed male predominance, higher platelet counts, lower hemoglobin levels and leukocyte counts, and a lower risk of thrombosis than patients with JAK2 and MPL mutations." (PMID 36359414, 2022). "It was observed that, the incidence of thrombosis among ET patients with CALR mutation was 7.5% (P=0.04)." (PMID 32292481, 2020). "Although MPL-mutated patients share a similar clinical picture with CALR-mutants, the latter group has a lower incidence of thrombosis, especially when compared to JAK2 V617F mutated counterpart (10.5 vs. 25.1%, respectively; p = 0.01)." (PMID 32629973, 2020). "Type 2-like CALR-mutated ET patients are younger and have lower risk of thrombosis despite higher platelet count if compared with those carrying JAK2 or type 1-like CALR mutation." (PMID 30074114, 2018). "Then again, we performed multivariable Cox regression analyses, examining age, sex, white blood cell count, hemoglobin, platelet count, lactate dehydrogenase, mutational status of JAK2/CALR, splenomegaly, and thrombosis." (PMID 27486987, 2016). "In ET patients, the CALR gene mutation appears to be associated with a reduced risk of thrombosis." (PMID 40572650, 2025). "Patients with CALR mutations are at lower risk of thrombosis than patients with JAK2V617F." (PMID 36908768, 2023). "Interestingly, a remarkably less frequent (p = 0.03) venous thrombosis was observed in patients with ET with CALR mutation than those with JAK2 mutation." (PMID 36611455, 2023). "Interestingly, in PMF, a recent meta-analysis found that CALR-mutated patients displayed a lower risk of splenomegaly (OR 0.47, 95% CI 0.29–0.78) and thrombosis (OR 0.52, 95% CI 0.29–0.92) when compared with JAK2-mutated patients." (PMID 35328626, 2022).
thrombosis (continued). "In addition, CALR mutated ET patients have longer overall survival (OS) and a lower risk of thrombosis compared to JAK2V617F positive patients, while CALR mutated PMF patients have longer OS compared with both JAK2V617F and MPL positive patients." (PMID 32781570, 2020). "In multivariate analysis, CALR (HR: 6.0 [2.3–16.1], p < 0.001) and thrombosis history (HR: 3.8 [95% CI: 1.3–11.4], p = 0.015) were both significant." (PMID 40074852, 2025). "Incidence rates of major arterial/venous thrombosis for JAK2, type 1/type 1-like CALR, type 2/type 2-like CALR, MPL-mutated and TN cases were 14%/8%, 11%/6%, 12%/9%, 13%/0%, and 6%/2%, respectively." (PMID 38238303, 2024). "Incidence rates of major arterial/venous thrombosis for JAK2, type 1/type 1-like CALR, type 2/type 2-like CALR, MPL-mutated and TN cases were 16%/13%, 7%/5%, 7%/2%, 13%/7%, and 18%/12%, respectively." (PMID 38238303, 2024). "Incidence rates of major arterial/venous thrombosis for JAK2, type 1/1-like CALR, type 2/2-like CALR, MPL-mutated and TN cases were 10%/8%, 10%/5%, 8%/4%, 14%/9% and 3%/2%, respectively." (PMID 38238287, 2024). "Arterial and venous thrombosis rates were significantly lower in CALR-mutated cases when compared with JAK2, whose thrombosis risk was otherwise similar to those with MPL mutation and TN (p < 0.01 and <0.01)." (PMID 38238303, 2024). "Quantitative and qualitative alterations of platelet, erythrocytes, leukocytes and endothelial cells, caused by gain-of-function mutations in JAK2, CALR or MPL, are implicated in the pathogenesis of thrombosis in MPN." (PMID 36768584, 2023). "Our patient had severe eosinophilia, thrombocytopenia, and thrombosis so we evaluated him for underlying primary HES by sending the FIP1L1–PDGFRA fusion gene, PDGFRB JAK2V617F mutation, CALR, and BCR‐ABL mutation." (PMID 35242558, 2022). "In particular, patients with ET and CALR mutation are known to have a lower risk of thrombosis compared to those with JAK2 V617F mutation; however, this seems to be different depending on the CALR mutant type." (PMID 36359414, 2022). "When comparing the clinical and hematological findings among CALR type 1, CALR type 2, and other CALR types, we found that three CALR mutation groups were similar in their sex ratio, IPSET-thrombosis risk score, HGB level and WBC counts." (PMID 31554376, 2019). "The JAK2+/CALR- group had higher white blood cell counts and levels of hemoglobin and lactate dehydrogenase and higher rates of splenomegaly and thrombosis than did the JAK2-/CALR-group." (PMID 27486987, 2016). "In multivariable analysis, the apparent protective association of CALR with thrombosis was not independent." (PMID 42058976, 2026). "Conversely, antiplatelets are avoided by physicians, mostly in cases of ET patients < 60 years who are JAK2-negative and without prior thrombosis (69.2%), who are young (<40 years of age) (50%), and CALR-mutated (23.1%)." (PMID 40094998, 2025). "Patients positive for CALR carries better prognosis and lower incidence of thrombosis." (PMID 40735564, 2025). "In another cohort of Italian patients, the risk of developing thrombosis was 2.5-fold higher in patients with ET (7.1% vs. 2.8%; p = 0.059), and 3.7-fold higher in patients with PV (10.5% vs. 2.8%; p = 0.001) with JAK2 mutations compared with CALR mutation." (PMID 36611455, 2023). "Nevertheless, the risk of thrombosis in CALR-mutated patients is considerably higher than that in the non-MPN-patient population." (PMID 35328626, 2022). "Based on retrospective observational studies, low-dose acetylsalicylic acid reduced incidence of venous thrombosis in JAK2V617F-mutated patients, while in CALR-mutated patients it did not affect the risk of thrombosis but was associated with a higher incidence of bleeding." (PMID 33498945, 2021). "This is in agreement with other studies which found that the incidence of thrombosis was 14.5% in JAK2 positive and 5% in CALR positive patients." (PMID 32292481, 2020).
thrombosis (continued). "Thrombosis-free survival and leukemia-free survival did not remarkably differ between groups (p = 0.14 and p = 0.20, respectively), with only 1 AML case occurring in the CALR-mutated subgroup after 7.73 years." (PMID 41463191, 2025). "The relationship of JAK2, CALR, and MPL mutations with thrombosis and splenomegaly is not clear." (PMID 35444868, 2022).